ATF6 (activating transcription factor 6)
Diseases named in the same sentence as ATF6 in open-access papers (continued):
Sharing a sentence is not in itself a finding about the gene and the disease.
glioblastoma (13 papers, 2016 to 2025). The most malignant astrocytic tumor (WHO grade IV). "Abnormal activities of all UPR effectors (PERK, IRE1α, and ATF6) have been shown to be implicated in the survival, metastasis, angiogenesis, and chemoresistance of glioblastoma, pancreatic, lung, colon/colorectal, and urological cancers at different stages of the disease." (PMID 40650182, 2025). "Of these, only ATF6 and IFNGR2 have been previously associated with glioblastoma viability and treatment resistance, while the remaining three have only been identified in other cancer types, which encourages further investigations." (PMID 36497269, 2022). "Another study showed that the activation of ATF6 in response to RT contributes to RT-induced GRP78 upregulation, and knockdown of ATF6 is sufficient to enhance RT-induced cell death in glioblastoma." (PMID 33003597, 2020). "We found that silencing ATF6 was sufficient to enhance the cytotoxic effects of radiation in glioblastoma." (PMID 26716508, 2016). "In this study, we found that by activating the ERSR, IR can contribute to adaptive survival signaling in glioblastoma through a mechanism that involves regulation of ATF6." (PMID 26716508, 2016). "Given the potential for ATF6 activation to mediate pro-survival signaling within glioblastoma, we silenced ATF6 and measured cell sensitivity to IR." (PMID 26716508, 2016). "Our findings support the notion of targeting the ATF6 pathway as a potential strategy to improve the efficacy of radiation therapy for glioblastoma." (PMID 26716508, 2016). "We also identified Notch1 as a novel transcriptional target of ATF6, with a potential role in promoting an anti-apoptotic phenotype in irradiated glioblastoma." (PMID 26716508, 2016). "As we previously demonstrated that EGFRvIII and RCN1 expression correlated with enhanced cell survival under ER stress conditions, we next evaluated whether ATF6 activity varied in high or low expressing RCN1 glioblastoma cells." (PMID 33801941, 2021). "To determine whether the reduction in ATF6 by EV-A71 was cell type dependent, we infected the glioblastoma cell line SF268 with EV-A71 BrCr and strain 4643." (PMID 29386036, 2018). "Similarly, ATF6α protects glioblastoma cells from UV-induced cell death by transactivating BiP, suggesting proto-oncogenic effects of ATF6α." (PMID 28860159, 2017). "While additional work is needed to validate the mechanisms by which Notch1 may be involved in promoting cell survival downstream of ATF6, this investigation supports other studies identifying Notch1 as a key component in therapeutic resistance in glioblastoma." (PMID 26716508, 2016). "The hypothesis that IR can induce the ERSR in glioblastoma was further supported by the observation of global activation of gene targets downstream of each arm of the ERSR: ATF6, IRE1 and PERK." (PMID 26716508, 2016). "Specifically, we identified the ATF6 pathway of the ER stress response as a radiation responsive signaling pathway, and NOTCH1 as a previously unidentified target of ATF6 with a potential role in mediating survival of glioblastoma cells during the radiation response." (PMID 26716508, 2016). "In particular, ATF6 activated by irradiation was associated with the upregulation of Notch1, which is not directly involved in UPR, but plays a pivotal role in cell proliferation and protection from apoptosis, and thus, contributes to the radioresistance of glioblastoma cells." (PMID 31540530, 2019). "Furthermore, this work highlights the potential for a new therapeutic strategy wherein targeting of the ERSR through inhibition of ATF6 may serve to enhance the efficacy of radiation therapy for glioblastoma." (PMID 26716508, 2016). "Thus, we hypothesized that the activation of ATF6 by radiation-induced ER stress could play a role in promoting the viability of irradiated glioblastoma." (PMID 26716508, 2016).
glioblastoma (continued). "A variety of natural, synthetic, and semisynthetic compounds either activating or suppressing IRE1α, PERK, ATF6, or GRP78 has been tested for the treatment of breast cancer, thyroid cancer, and glioma/glioblastoma." (PMID 40650182, 2025). "It was observed that the global expressions of ER stress-responsive genes, such as PERK, ATF4, ATF6, GADD34, and IRE1 were increased by the irradiation of glioblastoma cells." (PMID 31540530, 2019). "Our findings suggest that the ATF6 and IRE1 pathways are also activated in irradiated glioblastoma cell lines." (PMID 26716508, 2016). "Not only did we find that ATF6 transcriptional activity was enhanced in irradiated glioblastoma, but we also found accumulation of GRP78, a major target of ATF6, in a time and dose-dependent manner." (PMID 26716508, 2016). "We demonstrate that activation of the ATF6 pathway in irradiated glioblastoma cells accounts for increased GRP78 levels, and that ATF6 contributes to radioresistance in these cells." (PMID 26716508, 2016). "In the present study, DNMT2/TRDMT1 gene knockout-mediated effects were investigated during doxorubicin (DOX)-induced ER stress and PERK-, IRE1- and ATF6-orchestrated UPR in four genetically different cellular models of cancer (breast and cervical cancer, osteosarcoma and glioblastoma cells)." (PMID 36273376, 2023). "Desipramine promotes antitumor activity in glioblastoma by inducing autophagy through the PERK/eIF2α and ATF6 signaling pathways, and the rapid antidepressant effect of ketamine may also be associated with ER stress." (PMID 34947907, 2021). "In summary, these results demonstrate that ATF6 may be involved in regulating NOTCH1 mRNA and protein expression, and that Notch1 may play a role in promoting proliferation of irradiated glioblastoma cells." (PMID 26716508, 2016). "In our experiments, the treatment of A-172 glioblastoma cells for 24 and 48 h with sorafenib led to an increase in the expression of mRNA of the spliced form of the XBP1s transcription factor and did not change the expression of two other markers of ER-stress, ATF-4 and ATF-6." (PMID 36768736, 2023). "The cleavage effect was similar in three genotypes of EV-A71, including strain Tainan/4643/98 (isolated from a severe case), and in RD, HEK293T, MCF7, and glioblastoma SF268 cells (data not shown), suggesting that a reduction in ATF6 might not account for virulence or cell tropism." (PMID 29386036, 2018).
glioma (13 papers, 2012 to 2025). A benign or malignant brain and spinal cord tumor that arises from glial cells (astrocytes, oligodendrocytes, ependymal cells). "The UPR stress sensors IRE1, PERK, and ATF6 with their regulator GRP78 are upregulated in GB compared to lower grade gliomas and normal brain tissue." (PMID 39021040, 2024). "ATF6 signaling was described as modulating NOTCH signaling in gliomas in hypoxia conditions, leading to radiotherapy resistance of GSCs." (PMID 35784465, 2022). "Another example is the combination of TMZ with Fluoxetine (FLT), which activates ER stress through the ATF6-IRE1α-PERK cascade, causing an increase in early apoptosis levels and inhibition of cell proliferation in glioma." (PMID 35784465, 2022). "Glioma strongly expresses PERK, ATF4, ATF6, IRE1, and XBP1, and is associated with the malignant phenotype and poor prognosis." (PMID 33920356, 2021). "Levels of key UPR transcripts XBP-1, CHOP, ATF4, and ATF6 were only nominally detected in normal brain and unstressed U87 glioma cells, as reported by other studies." (PMID 24039668, 2013). "Literature reports indicate that ATF6 has divergent roles on lipogenesis and adipogenesis, so further evaluation of ATF6 in gliomas should prove important." (PMID 24039668, 2013). "Besides, the levels of Grp78, IRE1α, and ATF6-p50 were evaluated to assess ER stress in glioma cells." (PMID 40963691, 2025). "However, the same drug increased CHOP mRNA and protein expression upon activation of PERK-eIF2α-ATF4 and ATF6 cascade in glioma cells." (PMID 35456680, 2022). "In addition, 2OHOA treatment (150 μM; 24 h) also increased significantly ATF6 mRNA expression in human glioma (1321N1) cells." (PMID 23133576, 2012). "Furthermore, PDIA5 can promote ATF6 disulfide bond rearrangement of ATF6α under ER stress, maintaining its active conformation, and conferring chemotherapy resistance to cancer cells, thus affecting the progression of patients with glioma 19,20." (PMID 39247813, 2024). "The knockdown of PERK, ATF6, or IRE1 reduces glioma cell viability with a greater sensitivity to stress-induced cell death." (PMID 33920356, 2021). "In glioma cells, ER stress triggered by different drug treatments increases p-eIF2α in conjunction with elevated expression of other ER stress transducers (i.e. p-ERK, ATF6, p-IRE-1, GRP78, CHOP, XBP-1) enhancing glioma cell death." (PMID 31795417, 2019). "As target genes of three branches, DDIT3 (CHOP) and DNAJB9 (IRE1α-XBP1), but not SEL1L (ATF6) were obviously upregulated in glioma cells after treatment of S4, which declared ATF6 was not the main activated branch." (PMID 37386564, 2023). "Silencing PERK, but not IRE1α or ATF6α significantly enhanced DHA-induced cell death in glioma cells." (PMID 31519193, 2019). "However, IRE1α or ATF6 silencing did not enhance DHA-induced glioma cell death." (PMID 31519193, 2019).
lung carcinoma (13 papers, 2015 to 2025). "Mechanistically speaking, VLX1570 activated the PERK/IRE1/ATF6 pathway and induced ER stress in lung cancer cell lines." (PMID 34854221, 2022). "By setting the analytic option of the best perform threshold as a cutoff, it showed that high level of ATF6 expression predicts a better OS of the lung cancer patients as determined by three different ATF6 probes." (PMID 35625704, 2022). "Furthermore, IHC for co-expression analysis using anti-TUSC3 and anti-ATF6α antibodies in primary and metastasized lung cancer patient samples showed that enhanced and/or nuclear localized ATF6α protein was highly inversely correlated with TUSC3 expression." (PMID 30504895, 2018). "Additionally, the activation of ATF6α was more found to be in metastasized lung cancer patient samples." (PMID 30504895, 2018). "Therefore, the combined treatment of CDDP and TA in lung cancer cells may cause ER stress and induce apoptosis of tumor cells, mainly through the PERK-ATF4 and ATF6 pathways." (PMID 37885044, 2023). "To additionally investigate whether the ATF6 genes contribute to the pathogenesis of human lung cancer, we evaluated the prognostic value of ATF6 expression on overall survival (OS) of lung cancer patients using the publicly available dataset from Kaplan–Meier Plotter." (PMID 35625704, 2022). "We have detected the expression of ATF6 and ATF6B in both normal lung tissues and lung cancer tissues." (PMID 35625704, 2022). "Higher expression of ATF6 and ATF6B predicts a better and poorer OS of the lung cancer patients, respectively, indicating a possible tumor suppressor-like activity of ATF6 and an oncogenic property of the ATF6B for lung carcinogenesis." (PMID 35625704, 2022). "BDMC increases ER stress-associated proteins expression such as HSPA5, DDIT3, ERN1, ERN2/IRE-1β, ATF6, ATF6B and CASP4, which results in cell apoptosis in the human lung cancer NCI H460 cell line." (PMID 36497321, 2022). "The expression levels of GRP78, p‐PERK, IRE1, ATF6, ATF4 and p‐eIF2α were increased in all three human lung cancer cells in a dose‐dependent manner." (PMID 34854221, 2022). "Research results have shown that RRBP1 knockdown can affect the stability of ATF6 and GRP78 mRNA, thereby reducing the in vivo tumorigenicity of lung cancer cells." (PMID 31285390, 2019). "Utilizing TUSC3KO and TUSC3/HRD1 DKO cells, we found that ATF6α pathway, but not IRE1α and PERK pathways was selectively enhanced in TUSC3 deficient cells, possibly mediated the function of TUSC3 deficiency in lung cancer metastasis." (PMID 30504895, 2018). "Given the suppression of ATG7 by NASTRp, we further examined expression of ER stress markers, such as GRP78, CHOP, IRE1, PERK, ATF6 and XBP1, to determine whether NASTRp induces ER stress in lung cancer cells." (PMID 25897662, 2015). "Although IHC evaluation of the ATF6 and ATF6B in lung cancer tissues vs. case-matched non-cancerous tissues is somewhat inconclusive, the overall survival analysis for the lung cancer patients unraveled an opposite prognostic value between ATF6 and ATF6B." (PMID 35625704, 2022). "Together our results most clearly highlighted the importance of TEK, LDB2, ATF6 and UBQLN1 in NSCLC patient BE responses, underscoring the value of examining system-level gene interactions in order to better understand the determinants of lung cancer patient therapeutic responsiveness." (PMID 33075110, 2020). "LDB2 and ATF6 were not included in TCGA lung cancer datasets." (PMID 33075110, 2020).
type 2 diabetes (13 papers, 2011 to 2025). "Previous studies identified several SNPs in ATF6 associated with type 2 diabetes in different populations." (PMID 25302688, 2014). "ATF6 encodes UPR transducer unfolded protein that is related to the endoplasmic reticulum stress in the β-cell pathogenesis of type 2 diabetes." (PMID 23922971, 2013). "Because some groups have reported that polymorphisms and haplotypes of ATF6α are related to type 2 diabetes, ATF6α also appears to be important for the function of β cells." (PMID 24705207, 2013). "In a study of Pima Indians, a native American population with a high prevalence of type II diabetes, they found an association of variants in ATF6 with T2D." (PMID 21915177, 2012). "Studies in Pima Indian, Caucasians and African Americans identified several SNPs in DUSP12 and ATF6, located in chromosome 1q21-q23, were associated with type 2 diabetes." (PMID 21211013, 2011). "Therefore, we performed the present study, aiming to test if variants from DUSP12 and ATF6 played a role in the genetic susceptibility of type 2 diabetes in the Chinese." (PMID 21211013, 2011). "ATF6 is also the binding target of WFS1, a known type 2 diabetes susceptible gene, and mediates its effect on endoplasmic reticulum stress." (PMID 21211013, 2011). "It is now believed that ER stress-related diseases, including type II diabetes, result from the apoptosis of stressed cells owing to the interplay of the complex of three arm sensors (IRE1, PERK, and ATF6)." (PMID 34299638, 2021).
cardiac hypertrophy (12 papers, 2016 to 2025). "Instead, we observed that loss of ATF6α or ATF6β initially reduced cardiac hypertrophy but in the long term it accelerated cardiac decompensation and failure after pressure overload." (PMID 30765833, 2019). "We also hypothesized that the reduction in cardiac hypertrophy over 2 weeks due to a presumed alteration or reduction in ER protein production associated with the Atf6 or Atf6b null backgrounds might render these hearts more susceptible to heart failure with chronic hypertrophic stimulation." (PMID 30765833, 2019). "In conclusion, our study demonstrates that QRICH1 affects the progression of pathological cardiac hypertrophy by regulating the transcription of ATF6." (PMID 40355839, 2025). "As a transcription factor in ER stress, ATF6 has been reported to be involved in the regulation of cardiac hypertrophy." (PMID 40355839, 2025). "Taken together, these data suggest that QRICH1 exacerbates stress-induced pathological cardiac hypertrophy, potentially through the activation of the mTOR signaling pathway and its interaction with ATF6." (PMID 40355839, 2025). "In response to ISO, in QRICH1 KD mice, overexpression of ATF6 reactivated the mTOR signaling pathway, resulting in exacerbated cardiac hypertrophy and dysfunction." (PMID 40355839, 2025). "ATF-6, IRE1 and PERK-induced deterioration of the Ca2+ ion balance leads to cardiac hypertrophy caused by hyperthyroidism, and PERK was also essential during the experiments for avoiding TAC-induced congestive HF." (PMID 36034809, 2022). "Similar results were found in a more recent publication, where it was shown that deletion of ATF6α or ATF6β resulted in a reduction of pathological cardiac hypertrophy at early times after pressure overload." (PMID 32322217, 2020). "Similar results were found in a more recent publication where blunted pressure overload-induced cardiac hypertrophy and an accelerated progression to heart failure in ATF6 cKO mice." (PMID 32138230, 2020). "ATF6 cKO mice also exhibited exaggerated pathological cardiac hypertrophy and increased plasma cTnI." (PMID 30643122, 2019). "Hence, the beneficial effects of QRICH1 suppression on cardiac hypertrophy were reversed by ATF6 overexpression under growth stimuli." (PMID 40355839, 2025). "Accordingly, we speculated that QRICH1 influences the occurrence and development of cardiac hypertrophy by regulating ATF6." (PMID 40355839, 2025). "To confirm that the effect of QRICH1 promoting cardiac hypertrophy in vivo is due to the activation of ATF6 in cardiomyocytes under growth stimuli, we used dual AAV9 injections to evaluate the effects of ATF6 overexpression on cardiac phenotypes in QRICH1 KD mice." (PMID 40355839, 2025). "In fact, ATF6β has shown to play overlapping roles with ATF6α in settings of heart hypertrophy." (PMID 37025177, 2023). "Previous studies have demonstrated the role of ATF6α in cardiac alterations promoting cardiac hypertrophy, as its specific deletion in cardiac myocytes blunted the development of cardiac hypertrophy and impaired cardiac function in an animal model of transverse aortic constriction." (PMID 35897655, 2022). "ATF6 has been shown to be a primary adaptive sensor and responder to cardiac hypertrophy." (PMID 32138230, 2020). "The finding that ATF6 was required for exercise-induced physiological cardiac hypertrophy was surprising, as it’s a reactive growth process known to, if anything, decrease the accumulation of misfolded proteins, thus linking ATF6 activation primarily to the increase in protein synthesis." (PMID 32138230, 2020). "This was a bit of foreshadowing, and the first indication that ATF6 could be required for cardiac hypertrophy." (PMID 32138230, 2020). "Furthermore, ATF6 was necessary to prevent the accumulation of misfolded proteotoxic aggregates during pressure overload-induced pathological cardiac hypertrophy." (PMID 32138230, 2020).